HIF1A (hypoxia inducible factor 1 subunit alpha)
Diseases named in the same sentence as HIF1A in open-access papers (continued):
Sharing a sentence is not in itself a finding about the gene and the disease.
infection (continued). "In case of disease, oxidative stress, and possibly infection, excessive HIF1α expression might on the other hand promote germ cell apoptosis." (PMID 39631561, 2024). "However, unlike NFATc1, cytosolic HIF-1α was also decreased in case of pretreatment of cyclosporin A, thus indicating a role of calcineurin in the stabilization of HIF-1α following infection." (PMID 38750790, 2024). "Our transcriptomic data indicated that differential expression of known pathways of inflammation and infection response, such as HIF1α, MAPK, and PI3K signaling, may be impacted by TRP modulation." (PMID 39337422, 2024). "Hif1α is also targeted by the parasite-derived miRNAs fhe-miR-277b at 6 hrs post-infection." (PMID 39344634, 2024). "Modulating the level of HIF-1α in infected cells may be one of the potential therapeutic solutions to alleviate recurrent infections." (PMID 39456823, 2024). "HIF1α is normally induced by inflammation, infection, and/or hypoxia." (PMID 39769216, 2024). "However, growing evidence has shown that inflammation, infection and cancer can also facilitate HIF-1α stabilization." (PMID 38555419, 2024). "However, as far as expression is concerned, infection led to significant enhancement in HIF-1α expression over control cells during late hours of infection (2.8-fold at 48 h postinfection, p = 0.000246, F = 15.90)." (PMID 38750790, 2024). "Specifically, in vitro infection induced a change in the expression of 70 HIF1α target genes (66 genes whose expression is promoted by HIF1α and 4 whose expression is repressed by HIF1α), providing evidence for the activation of the HIF1α protein in response to R. delemar infection." (PMID 38902255, 2024). "In addition, increased expression of Hypoxia-inducible factor-1 (HIF-1α) due to infection resulted in intestinal inflammation, because HIF-1α is known to suppress the activation of β-catenin, causing a downregulation of Wnt." (PMID 37107286, 2023). "However, in the context of long-term infection, we observed a significant increase in both mRNA expression and protein levels of HIF-1α compared to control." (PMID 37626956, 2023). "Furthermore, recent studies reported that HIF-1α promoted infection with various viruses, including severe acute respiratory syndrome coronavirus 2 (SARS-CoV-2) and respiratory syncytial virus." (PMID 37615898, 2023). "Understanding the hypoxia and HIF1 α modulation in both mild and severe infections by respiratory viruses may allow the development of new therapeutic approaches for the most severe cases of respiratory syndromes." (PMID 36851739, 2023). "HIF-1α may indirectly facilitate this process as infection (and replication) was decreased in HIF-1α-mutant iPSC-CMs." (PMID 36814444, 2023). "The upregulation of HIF1-α under hypoxic conditions may impact Salmonella's binding and infection by affecting tight junctions, which serve as entry sites for the bacteria." (PMID 37875985, 2023). "Interestingly, HIF-1α stabilization was reduced in SARS-CoV-2 cells treated with DMOG at 24 h postinfection at intermediate doses, indicating an infection-associated shift in the apparent IC50 of this agent." (PMID 37417946, 2023). "Therefore, this study focused on assessing the roles of HIF-1α in the infection of hypoxic tilapia with L. monocytogenes." (PMID 37681973, 2023). "HIF-1α also plays an anti-infection role in innate immune cells when they sense microorganisms." (PMID 36761171, 2022). "However, at 24 h and 48 h post-infection, the increasing infection dose seemed to result in higher HIF1α protein levels." (PMID 35755850, 2022). "The fact that HIF1α is degraded in infected normoxic macrophages at later time points of infection might be due to the intracellular lifestyle of C. burnetii, which hides in an intracellular vacuole." (PMID 35755850, 2022). "Similarly, at 48 h post-infection, the HIF1α protein level was increased in hypoxic BMDM infected with heat-killed C. burnetii compared to BMDM infected with viable C. burnetii." (PMID 35755850, 2022).
infection (continued). "In contrast, knocking down HIF-1α decreases the expression of aerobic glycolysis genes in activated macrophages, which leads to the metabolic preference of oxidative phosphorylation and the failure to resist infection." (PMID 37073169, 2022). "For example, HIF-1α mediates excessive activation of innate immunity, leading to dysregulated biological function of innate immune cells, such as antigen presentation and anti-infection." (PMID 36761171, 2022). "It is speculated that infection-induced NF-ĸB signaling promotes the normoxic stabilization of HIF-1α in activated macrophages." (PMID 37073169, 2022). "In normoxic BMDM, C. burnetii led to HIF1α stabilization only at 4 h post-infection." (PMID 35755850, 2022). "Thus, we investigated the impact of myeloid-lineage conditional knockouts of Hif1a or Vhl on pathologic changes to bone architecture using microCT at day 14 post-infection." (PMID 36204648, 2022). "HIF-1α is a significant regulator of energy homeostasis in response to hypoxic and non-hypoxic stimuli, which has played an essential role in the development of infections by activating the host functional response, thus invading the pathogens." (PMID 34898382, 2022). "After infection for 2 h, the HIF-1α-dependent glycolysis pathway may be involved in activated macrophages induced by pathogenic leptospiral infection." (PMID 35638785, 2022). "Differential levels of HIF-1α were noticed during the course of infection in mice." (PMID 36417626, 2022). "In addition, the levels of filaggrin, VEGF, MIP-1β, RANTES/CCL5, HIF-1α and IL-1β were identified as infection biomarker molecules with AUC values > 0.72, having the next values of specificity (> 79%) and sensitivity (> 55%)." (PMID 36482106, 2022). "To confirm the role of hypoxia pathways in infection tolerance, we explored whether we could shift infected embryos to a susceptible state during 1,4‐DPCA treatment using the research‐grade HIF‐1α inhibitor, sc‐205346." (PMID 35706367, 2022). "To determine whether HIF-1α is required for IFN-γ-independent control of infection we co-cultured Ifng-/- CD4 T cells with wild-type or Hif1a-/- BMDMs." (PMID 35877763, 2022). "HIF-1α plays an important role in the regulation of the NF-κB pathway, which is important in preventing excessive and harmful proinflammatory responses during infection and inflammation." (PMID 35453567, 2022). "Hypoxia was also significantly increased when infection occurs, as indicated by HIF1α." (PMID 35077516, 2022). "To better understand the therapeutic mechanism of HSSD in H1N1-infected mice, we measured the expressions of TLR4/NF-κB p65 and HIF-1α/IL17 pathways according to the prediction of network pharmacology results in lung tissues on the day 5 post-infection by using RT-qPCR and IHC staining." (PMID 36386710, 2022). "The HIF-1α mRNA levels were significantly upregulated in L. interrogans-infected BMDMs compared to in uninfected BMDMs (P < 0.005) and L. biflexa-infected BMDMs (P < 0.01, 2-h infection; P < 0.005 for 24-h infection)." (PMID 35638785, 2022). "Mice challenged with Af-beads also displayed increased expression of Hif1a in the lungs on day 3 when compared to N-bead controls (dotted line), although the transcript levels decreased on day 14 post-infection, a finding in line with the smaller granuloma areas observed at this timepoint." (PMID 36275017, 2022). "Interestingly, HIF-1α was reported to inhibit the infection of lung cells by SARS-CoV-2 by reducing ACE2 viral receptor expression." (PMID 36091390, 2022). "During the acute phase of infection, HIF-1α activity is increased in Drosophila macrophages." (PMID 37073169, 2022). "Furthermore, similar to the early time point (4 h) of infection, CoCl2 stabilized the HIF-1α protein, proven by immunoblotting assay in both concentrations of CoCl2-treated cells." (PMID 35631117, 2022).
infection (continued). "Therefore, HIF-1α stabilization upon infection is a crucial event to elicit the metabolic switch toward aerobic glycolysis for rapid energy production to support effective phagocytosis." (PMID 37073169, 2022). "HIF1α stabilization has previously been reported after infection with other viruses." (PMID 36324747, 2022). "In addition, microarray analysis of early exhausted T-cells within the LCMV mouse model demonstrated increased CPT1α and HIF1α gene expression levels in exhausted T-cells compared to memory ones early during infection." (PMID 35794135, 2022). "Hypoxia may regulate the innate immune response under conditions of infection or inflammation by producing HIF-1α to regulate TLR expression and function." (PMID 36291237, 2022). "Myeloid but not neutrophil-specific hypoxia-inducible factor (HIF)-1α-deficient mice increased bacterial loads in the lungs and distant organs after infection of K. pneumoniae as compared to control mice, pointing to a role of HIF-1α in macrophages." (PMID 36506034, 2022). "Therefore, we infected BMDM at an MOI of 10, 50 or 100 under hypoxia and analyzed the infection by immunofluorescence and the HIF1α protein level by immunoblot." (PMID 35755850, 2022). "As a control, Hif1a mRNA levels were reduced after infection of Hif1afl/fL lysm cre BMM." (PMID 36121152, 2022). "Importantly, HIF‐1α is thought to be important in hypoxic environments or in innate immune responses to infection." (PMID 35388602, 2022). "In neutrophils, HIF-1α promotes cell survival and phagocytosis, which might favor the control of infections with different pathogens by these cells." (PMID 35624725, 2022). "Compared to control mice, the absence of HIF1α in NK cells resulted in susceptibility to infection, but this was not due to an impaired effector response." (PMID 34396954, 2021). "To explore whether Ms_Rv0580c can induce hypoxia, we examined the expression of hypoxia-inducible factor, HIF-1α, after infection of macrophages with recombinant strains." (PMID 33535567, 2021). "Moreover, this study evaluated the effect of HIF-1α after viral entry by inducing hypoxia 8 h post-infection, which showed a 90% reduction of viral RNA levels, and decreased the release of viral particles compared to during normoxic conditions." (PMID 34360716, 2021). "Thus, HIF1α supports survival in NK cells through providing optimal glucose metabolism during pathogen infection." (PMID 34396954, 2021). "Moreover, the effect of SARS-CoV-2 ORF3a on the regulation of VSV replication and infection through inducing HIF-1α production and proinflammatory cytokine production was evaluated." (PMID 34408131, 2021). "Therefore, our work suggests that MFN2 functions in the suppression of macrophage differentiation into the M2 phenotype as well as driving aerobic glycolysis and inflammatory responses through HIF-1α during infection." (PMID 33972668, 2021). "In addition, we are only beginning to understand the role of infection-induced HIF1α stabilization in host–pathogen interaction." (PMID 33125509, 2021). "(E) CD69 and HIF1α was determined at day 1.5 post-infection (pi)." (PMID 34396954, 2021). "Moreover, the frequency of NOS2+ in HIF-1α KO macrophages was also diminished at the later phase of infection." (PMID 33989349, 2021). "The expression of Hif-1α was unaltered at 49 dpi, but significantly increased in the ileum of the single-infected group at 21 dpi and both infection groups at 35 dpi." (PMID 34649607, 2021). "HIF-1α activation is observed upon infection with several other viruses." (PMID 34517756, 2021). "It is noteworthy that HIF-1α also extensively promotes infection of other viruses." (PMID 35069552, 2021).
infection (continued). "In contrast, during the early phase of infection, C. trachomatis enhanced HIF1α stabilization." (PMID 33125509, 2021). "Loss of HIF1α did not affect NK cell proliferation during in vivo infection and in vitro cytokine stimulation." (PMID 34396954, 2021). "The MFN2-induced aerobic glycolysis during infection is at least partly mediated by HIF-1α." (PMID 34482801, 2021). "Therefore, the contribution of HIF1α to NK cell metabolism is incompletely understood, particularly during the pathogen infection." (PMID 34396954, 2021). "The activation of HIF-1α has been shown to be a generalized response to infection." (PMID 33718271, 2021). "Notably, the expression of HIF-1α was positively correlated with the production of immune and inflammatory cytokines upon the infection of SARS-CoV-2, VSV, and HSV-1 and the treatment of poly(I: C)." (PMID 34408131, 2021). "In general, HIF-1α promotes a pro-inflammatory state, which may improve mycobacterial clearance early in infection, but also induces pathological inflammation and immune exhaustion during chronic infection." (PMID 33552087, 2020). "However, when they encounter with low oxygen pressure in the site of infection they increase HIF-1α expression promoting their phagocytic activity." (PMID 33139969, 2020). "In our study HIF-1α protein was induced in response to infection with P. histicola (in hypoxic conditions) mediated by TLR5, suggesting that TLR5 in addition to inducing inflammation may also have a regulatory role in the inflammatory response through HIF-1α." (PMID 33031374, 2020). "Additionally, we observed that the down-regulation of HIF expression only occured late after infection (24 h post-infection); in fact, HIF-1α, and particularly HIF-2α, were up-regulated in hypoxic DLD-1 and HCT116 cells at eight hours post-infection." (PMID 32244697, 2020). "Infection with IAV H1N1 resulted in the translocation of HIF-1α to the nucleus during normoxia." (PMID 33135539, 2020). "However, in cells transfected with siRNA targeting TLR5, HiF-1α was significantly reduced in response to infection with P. histicola (30 min, p<0.001) suggesting that P. histicola induced TLR5 signalling was mediated by HIF-1α." (PMID 33031374, 2020). "Whereas induction of HIF-1α promotes a pro-inflammatory state, which may improve mycobacterial clearance early during the course of infection, it can also lead to pathological inflammation and immune exhaustion during chronic infection." (PMID 33552087, 2020). "Together these studies suggest that parasites are able to manipulate HIF‐1α levels in a variety of ways as part of their circumvention of the host immune response, creating an opportunity to target HIF‐1α to improve infection outcome that has yet to be fully explored." (PMID 32633061, 2020). "Importantly, infections with KSHV have been reported to upregulate the transcript levels of both HIF-1α and HIF-2α in endothelial cells." (PMID 33135539, 2020). "Human fibroblasts have shown increased HIF-1α expression after infection with HCMV." (PMID 33135539, 2020). "During early infection, HIF‐1α stabilisation is beneficial for innate immune control of TB." (PMID 32633061, 2020). "However, only infection with viable H. capsulatum sustained HIF-1α protein in MDM up to 24 h postinfection (hpi), while incubation with heat-killed yeasts did not." (PMID 31036602, 2019). "In the context of infection, HIF-1α is crucial to mounting a proper innate immune response." (PMID 31036602, 2019). "Importantly, the macrophage-specific knockdown of either Hif1α or Ldh suppressed the occurrence of an infection-induced increase in circulating lactate titer." (PMID 31609200, 2019). "We next tested whether injury- and infection-induced tnfa are Hif-1α and cyclooxygenase dependent processes." (PMID 31611882, 2019). "Moreover, pathogen load in Hml >Hif1α[RNAi] flies was substantially elevated when compared with that in controls at the second and third day post-infection." (PMID 31609200, 2019).
infection (continued). "Thus, our objective was to elucidate the role of HIF1α during host infection by MHV68 and its virus life cycle using both in vitro and in vivo infection models." (PMID 31809522, 2019). "First, we ascertained if infection of MDM stimulated stabilization of HIF-1α in normoxia." (PMID 31036602, 2019). "HIF-1α stabilization in neutrophils induces NO production after infection by Mm." (PMID 30915076, 2019). "In order to define whether HIF1α plays a role during MHV68 infection, we examined virus replication in lungs and latent virus establishment and reactivation from splenocytes." (PMID 31809522, 2019). "Therefore, we focused on the characterization of systemic carbohydrate metabolism during the acute phase of infection in Hml >Hif1α[RNAi] and Hml >Ldh[RNAi] flies." (PMID 31609200, 2019). "The results showed that HIF1α transcriptional activity decreased to 53% as a result of HG(4d)+LG(4d) treatment compared to the LG(8d) group, and the infection of either ERβ lentivirus (↑ERβ) or SOD2 lentivirus (↑SOD2), or ERβ agonist DPN treatment, completely restored this effect." (PMID 31396159, 2019). "We next determined whether HIF1α contributes to the alteration of glycolytic pathway activity in differentiated macrophages during different pathogen infections." (PMID 29483608, 2018). "Addition of MitoTEMPO to cells infected with either HIV-1wt or integrase-deficient HIV-1 abolished the induction of HIF-1α activity triggered by infection but did not affect the percentage of infected cells (~46% under all conditions)." (PMID 30206166, 2018). "HIF1α deficiency significantly increases the production of IL-10 protein by macrophages following infection but not IL-10 mRNA expression, indicating that IL-10 secretion is regulated by HIF1α through post-transcriptional regulatory mechanisms." (PMID 29483608, 2018). "After infection of control and HIF-1α-silenced cells with HIV-1, we observed that viral replication was severely impaired in silenced cells, as revealed by analyzing the percentage of infected cells and the amount of p24 released into the cell culture supernatant at day 3 postinfection." (PMID 30206166, 2018). "HIF1α−/− mice displayed an earlier onset and a markedly more severe course of infection." (PMID 29483608, 2018). "To further determine whether NleB-enhanced cellular glucose uptake is dependent on HIF-1α, we knocked-down HIF-1α in RCC4 cells by infection with HIF-1α shRNA-2 lentivirus." (PMID 30125331, 2018). "Moreover, we show that the reverse transcription (RT) inhibitors efavirenz and nevirapine abolish the response to infection, further supporting the idea that reverse-transcribed DNA is the main trigger of HIF-1α activity." (PMID 30206166, 2018). "Expression of HIF1A was increased by infection (main effect, p = 0.041)." (PMID 30778359, 2018). "In RCC4 cells (which contain both HIF-1α and HIF-2α), ΔnleBE+pNleB infection caused higher cellular uptake of 2-NBDG (a fluorescence glucose analog) as quantified by flow cytometry (FACS) compared with cells infected with the control (nleBE+vector or ΔnleBE+pNleB-DXD strains) (p = 0.0114)." (PMID 30125331, 2018). "However, mice with a myeloid‐cell‐specific defect in HIF‐1α are unable to mount a trained immunity against S. aureus and succumb to the infection." (PMID 29976786, 2018). "Therefore, finding a clear correlation between hypoxia, HIF-1α expression, inflammatory responses, and infection is complex, and multiple cellular processes have to be taken into consideration." (PMID 30082478, 2018). "Hif1a-/- BMDM have a modest defect in transcript levels of Cox2 during infection, which could explain a defect in production of PGE2." (PMID 29370315, 2018). "The peak relative level of nuclear HIF-1α was observed 24 h post infection (P<0.01)." (PMID 28536432, 2017). "Moreover, infection decreased the percentage of both control cells and HIF-1α knockdown cells in G2/M phase to the same extent." (PMID 28401064, 2017).